RNU6-510P (RNA, U6 small nuclear 510, pseudogene)
Gene: Small nuclear RNA gene on chromosome 1 (37,991,462 to 37,991,569, forward strand). Ensembl gene ENSG00000212541.
Homologues: Orthologues: chimpanzee U6 (89% identical). Paralogues in human: RNU6-1145P (77% identical), RNU6-38P (76% identical), RNU6-1214P (75% identical), RNU6-340P (75% identical), RNU6-393P (75% identical), RNU6-616P (75% identical), RNU6-639P (75% identical), RNU6-86P (75% identical), RNU6-1316P (74% identical), RNU6-16P (74% identical), RNU6-20P (74% identical), RNU6-21P (74% identical), and 1286 more.